CLPTM1L (CLPTM1 like)
Diseases named in the same sentence as CLPTM1L in open-access papers (continued):
Sharing a sentence is not in itself a finding about the gene and the disease.
tumor (24 papers, 2012 to 2025). "Expression analyses showed that the CLPTM1L gene contained in this region was more expressed in people with the risk variants, pointing to CLPTM1L playing a role in tumor development." (PMID 28781888, 2017). "The CLPTM1L gene variant rs402710 is associated with higher DNA adduct formation in tumor adjacent lung tissue." (PMID 24194831, 2013). "A recent study found that a genetic variant within the CLPTM1L gene (rs402710) is associated with the accumulation of DNA adducts in tumor adjacent lung tissue." (PMID 22675468, 2012). "Sensitivity to cisplatin induced apoptosis was also increased with loss of CLPTM1L expression by shRNA in H838 tumor cells, measured by colorimetric Caspase 3/7 activity assay." (PMID 22675468, 2012). "DAP1 has been implicated in tumor cell apoptosis, suggesting that CLPTM1L may regulate cisplatin-induced apoptosis and cisplatin sensitivity of cervical cancer cells through DAP1." (PMID 39346724, 2024). "Previous studies have highlighted SREBP1’s crucial role in regulating cholesterol and fatty acid metabolism, implicating a potential involvement of CLPTM1L in fatty acid biosynthesis, which is essential for tumor cell proliferation and energy demands." (PMID 40550808, 2025). "Currently, the role of cleft-lip and palate transmembrane protein-1-like (CLPTM1L) rs401681 in various tumor types, particularly lung cancer, has garnered significant attention." (PMID 39113849, 2024). "Cleft lip and palate transmembrane protein 1-like (CLPTM1L)/cisplatin resistance-related protein 9 (CRR9) are cytoprotective oncofetal protein and chemo-resistance factors on the tumor cell surface." (PMID 37497408, 2023). "Treatment of mice (weekly, I.P.)with 10 mg/kg 102-5 anti-CLPTM1L resulted in inhibition of tumor growth over 8 weeks." (PMID 33654182, 2021). "We have recently identified surface-expressed CLPTM1L to be a tumor-specific cytoprotective and chemoresistance factor in pancreatic and other tumor types that can be further induced by genotoxic or endoplasmic reticular stress." (PMID 33654182, 2021). "With combination treatments of carboplatin following anti-CLPTM1L treatment, tumor load was decreased (0.23-fold) over 35 days compared to mice treated with carboplatin alone, in which tumor load increased slightly by an average of 1.23-fold (T-test p < 0.05)." (PMID 33654182, 2021). "Our previous work and that of others has established CLPTM1L (cleft lip and palate transmembrane protein 1-like)/CRR9 (cisplatin resistance related protein 9) as a cytoprotective oncofetal protein that is present on the tumor cell surface." (PMID 33654182, 2021). "In MCW-OV-SL3-CisR platinum resistant xenografts, cisplatin significantly inhibited tumor growth only in combination therapy with 102-5 anti-CLPTM1L." (PMID 33654182, 2021). "Control mice had an average increase in tumor load of 2.45-fold at day 42, while 102-5 anti-CLPTM1L-treated mice had an average of 0.90-fold relative tumor load at day 42 (T-test p < 0.005) (Paired t-test across time points, p = 0.001)." (PMID 33654182, 2021). "CLPTM1L is present in extracellular vesicle fractions of tumor culture supernatants and in patients’ serum with increasing abundance upon chemotherapy treatment." (PMID 33654182, 2021). "Tumor growth and volumes, monitored over 24 days post-inoculation, were significantly inhibited by both cisplatin and 102-5 anti-CLPTM1L either as individual monotherapies or as a combination." (PMID 33654182, 2021). "We have shown that in tumor cells depleted of CLPTM1L, intercellular CLPTM1L from supernatants becomes important for cytoprotection against chemotherapeutic toxicity." (PMID 33654182, 2021). "Except for TERT and CLPTM1L, genes shared by neoplasm diseases and other diseases in the two modules are different, reflecting diverse mechanisms underlying neoplasms of different tissues and their multimorbidities." (PMID 34225788, 2021).
tumor (continued). "Restriction of CLPTM1L surface expression to stem cell populations and tumor cells presents the potential to target quiescent residual tumor cells and to eliminate inherent or acquired resistance to multiple chemotherapeutic drugs." (PMID 33654182, 2021). "The combination of CLPTM1L shRNA and local IR had a greater effect on reducing A549 xenograft tumor size than treatment with local IR alone." (PMID 32943060, 2020). "The expression pattern of the CLPTM1L molecules on the surfaces of the tumor cells appeared very diffuse in most cases." (PMID 23300716, 2012). "Expression of CLPTM1L mRNA in NSCLC patient tumors was compared to that of matched tumor-adjacent tissues by qPCR." (PMID 22675468, 2012). "Out of the 151 patients who provided specimens, 136 (86.8%) showed CLPTM1L expression and CLPTM1L was overexpressed in tumor tissues compared to adjacent tissues, which was statistically significant different (p = 0.000)." (PMID 23300716, 2012). "Moreover, immunohistochemical analysis with CLPTM1L antibodies demonstrated that CLPTM1L predominantly localized in the cytoplasm of tumor cells, with minimal expression in adjacent normal tissues." (PMID 40550808, 2025). "Moreover, while our data indicate a significant increase in CLPTM1L mRNA expression in cervical cancer tumor tissues compared with normal cervical tissues, the differential protein expression of CLPTM1L also necessitates investigation." (PMID 39346724, 2024). "High CLPTM1L expression was also associated with poor overall survival with a hazard ratio of 1.3 (p = 0.012), particularly for those patients with a CA125 tumor marker level below the lowest quartile (HR = 2.14, p = 0.003)." (PMID 33654182, 2021). "While increased CLPTM1L in the extracellular vesicles fraction of treated patients may be the result of generally increased vesicle shedding by tumor cells, we have demonstrated the concept that extracellular CLPTM1L can transfer chemoresistance." (PMID 33654182, 2021). "CLPTM1L expression was strongly associated with the tumor grades of differentiation but not smoking status." (PMID 25233467, 2014). "Functional assays reveal that CLPTM1L overexpression significantly enhances NPC cell proliferation, migration and invasion, whereas its knockdown induces apoptosis and suppresses tumor growth." (PMID 40550808, 2025). "Immunofluorescence staining of tumor sections demonstrated decreased Ki-67 (+) and increased cleaved-PARP (+) cells, indicating reduced cell proliferation and increased apoptosis in CLPTM1L-depleted tumors." (PMID 40550808, 2025). "Several other studies have demonstrated robust overexpression of CLPTM1L on the surface of malignant cells in a variety of tumor types with minimal non-surface expression or no expression in normal tissues." (PMID 33654182, 2021). "To determine whether knockdown of CLPTM1L increases the radiosensitivity of NSCLC tumors in vivo, we generated a xenograft tumor model using male athymic (nu/nu) BALB/c mice." (PMID 32943060, 2020).
adenocarcinoma (4 papers, 2010 to 2016). A common cancer characterized by the presence of malignant glandular cells. "We found that CLPTM1L was expressed in cancerous lung tissue, most intensely in adenocarcinoma tissue." (PMID 23300716, 2012).
lip (3 papers, 2011 to 2014). "The human 5p15.33 locus contains two well-known genes, the telomerase reverse transcriptase (TERT) and cleft lip and palate transmembrane 1-like (CLPTM1L) genes, which have been implicated in carcinogenesis." (PMID 24386361, 2013). "The region on chromosome 5p15.33 contains two genes, CLPTM1L - cleft lip and palate transmembrane 1 like gene and TERT - human telomerase reverse transcriptase gene." (PMID 21966413, 2011).
CLPTM1L also shares sentences with these, for which no sentence is quoted: esophageal cancer (2 papers); prostate carcinoma (2); acute lymphoblastic leukemia (1); ankylosing spondylitis (1); B-cell neoplasm (1); basal cell carcinoma (1); cancer of the brain (1); cervical dysplasia (1); chronic lymphocytic leukemia (1); Crohn disease (1); cutaneous squamous cell carcinoma (1); endometrioid ovarian cancer (1); esophageal squamous cell carcinoma (1); gastric cancer (1); glioblastoma (1); head and neck cancer (1); hepatocellular carcinoma (1); idiopathic pulmonary fibrosis (1); infection (1); kidney cancer (1); laryngeal squamous cell carcinoma (1); lung squamous cell carcinoma (1); mantle cell lymphoma (1); Multiple Myeloma (1); myeloproliferative neoplasm (1); nevus (1); nicotine dependence (1); primary biliary cirrhosis (1); psoriasis (1); renal cell carcinoma (1).
A further 8 diseases each share a sentence with CLPTM1L in 1 paper.